IFNG (interferon gamma)
Diseases named in the same sentence as IFNG in open-access papers (continued):
Sharing a sentence is not in itself a finding about the gene and the disease.
uveitis (continued). "Daclizumab treatment in endotoxin-induced uveitis reduced Th1 lymphocytes-related cytokines, such as Interleukin-2 and Interferon gamma, by about 60–70% and presented a preventive role in endotoxin-induced oxidative stress." (PMID 24595020, 2014). "The combination of the IL-10/IL-6 and IL-10/IFNγ ratios was highly informative for discriminating PIOL/OCL from uveitis samples and for therapeutic follow up of PIOL." (PMID 23405064, 2013). "Our prior data demonstrated an important protective role for IFNγ in uveitis in a murine model of progressive spondyloarthritis." (PMID 22269151, 2012). "Collectively, our data support an important role for IL-17 in the pathogenesis of PG-induced uveitis, which is negatively regulated by IFNγ." (PMID 22269151, 2012). "IP-10, IFNγ, IL-6, G-CSF, TNFα IL-8, IL-1ra, and GM-CSF emerged as the most promising cytokines to be further investigated for treatment of BD- and VKH-associated uveitis." (PMID 32210963, 2020). "The percentage of CD8+IL-17hi (p = 0.027) and CD8+ interferon gamma (IFNγ)hi cells (p = 0.022) were significantly decreased in the IRT-5-treated uveitis models and the percentage of CD8+IFNγhi cells was markedly reduced (p = 0.036) in IRT-5-treated dry eye model." (PMID 29068389, 2017). "Furthermore, IFNγ knockout (KO) mice had significantly greater endotoxin-induced uveitis as compared with wild-type mice, and the injection of murine IFNγ suppressed the severity of endotoxin-induced uveitis in both wild-type and KO mice." (PMID 24886820, 2014). "Finally, the graphic representation of the combination of the Logarithmic (Log10) conversion of IL-10/IL-6 and IL-10/IFNγ ratios helps to cluster the PIOL/OCL versus uveitis patients at diagnosis, with the upper right cluster specific for PIOL/OCL patients." (PMID 23405064, 2013). "IL-6 was detected in 100% of the uveitis samples, IL-10 in 60%, and IFNγ in 48%." (PMID 23405064, 2013). "Recent studies have shown that retinal cells could suppress uveitis through interferon-gamma-mediated production of IL-27 in target tissues, while IL-27 expression was also upregulated during uveitis." (PMID 22876110, 2012). "The worsened uveitis that occurs in IFNγ KO mice is inhibited by in vivo blockade of IL-17." (PMID 22269151, 2012). "No randomised controlled trial (RCT) has previously evaluated the effect of antitubercular therapy (ATT) in patients with uveitis of undetermined cause who tested positive on interferon-gamma release assays (IGRA), despite the absence of other identifiable causes of uveitis." (PMID 41018498, 2025). "The present study investigated the role of IFNG +874A/T polymorphisms among 153 HTLV-1-infected individuals (33 clinically diagnosed with TSP/HAM, 22 with rheumatologic manifestations, 2 with dermatitis, 1 with uveitis, and 95 asymptomatic patients) and 300 healthy control individuals." (PMID 29867783, 2018). "In this regard, our finding that treatment with Gal-8 during the course of uveitis markedly decreases the soluble levels of both the TH1 cytokine, IFNγ, as well as the TH17 cytokine, IL-17A, in the retina is of interest." (PMID 26126176, 2015). "Despite the significant differences in the median IL-10/IL-6 and IL-10/IFNγ ratios between PIOL/OCL and uveitis samples, the range of values between these groups overlapped." (PMID 23405064, 2013). "In the second part of this work, we analyzed the Th1/Th2 cytokine profile, including IL-10, IL-6 and IFNγ, in vitreous and aqueous humor samples from patients with PIOL, oculocerebral lymphoma (OCL), uveitis, and retinal detachment (as controls)." (PMID 23405064, 2013). "The combination of the IL-10/IL-6 and IL-10/IFNγ ratios was highly informative in its discrimination between PIOL/OCL and uveitis samples." (PMID 23405064, 2013). "Subjects with any form of uveitis, a positive TB interferon-gamma release assay or tuberculin skin test, and negative evaluation for other causes of uveitis were included." (PMID 28980216, 2017).
uveitis (continued). "Vitreous samples from 60 patients with PIOL (n = 17), OCL (n = 9), uveitis (n = 23) or retinal detachment (RD) without hemorrhage (n = 11) were analyzed for IL-2, IL-4, IL-6, IL-10, IFNγ, and TNFα concentrations by CBA." (PMID 23405064, 2013). "Because IFNγ and IL-6 seemed to increase the IL-10 level of discrimination, we calculated IL-10/IL-6 and IL-10/IFNγ ratios to improve discrimination of PIOL/OCL versus uveitis patients." (PMID 23405064, 2013). "Consistent with our prior report, retinal damage such as folding of the inner nuclear layer (INL) and outer nuclear layer (ONL) layers is also a pathological feature of uveitis in mice lacking IFNγ, which is graded using a structural scoring system." (PMID 22269151, 2012). "According to our findings, VEGF, TNFα, and IFNγ had no role in BD uveitis." (PMID 28468317, 2017). "In conclusion, the combination of the IL-10/IL-6 and IL-10/IFNγ ratios could be very helpful as an initial screening to rule out PIOL in uveitis patients." (PMID 23405064, 2013). "Given the counter-regulatory role for IFNγ on the Th17 responses, the present study was designed to examine whether the exacerbated uveitis that occurs in the absence of IFNγ results from an imbalance of the Th17 response." (PMID 22269151, 2012). "Here, we tested the extent to which IL-17 mediates uveitis occurring in the absence of IFNγ." (PMID 22269151, 2012). "Given the regulatory role of IFNγ on the Th17 response and the current focus of anti-interleukin-17 therapeutics in patients with uveitis and spondyloarthritis, we sought to determine the extent to which interleukin (IL)-17 mediates uveitis in the absence of IFNγ." (PMID 22269151, 2012). "Given the emerging data supporting a key role for IL-17 in patients with AS and related spondyloarthropathies, we tested whether systemically administered blocking antibody to IL-17 would alter the onset and/or severity of uveitis occurring in the absence of IFNγ." (PMID 22269151, 2012).
chlamydial infection (97 papers, 2008 to 2026). "Of these murine trials, the most commonly measured host cytokine in response to chlamydial infection is IFNγ, where the expression of IFNγ has been associated with protection against chlamydial disease." (PMID 33102563, 2020). "Whilst Th1 responses and IFNG are essential for controlling chlamydial infection, excessive responses are thought to cause collateral tissue damage and contribute to chlamydial pathology." (PMID 28966918, 2017). "In humans and mice, resistance to chlamydial infection is associated with Th1-type cytokines, such as interferon γ (IFNγ), which promote cytotoxic T cell responses (Perry, Feilzer & Caldwell, 1997)." (PMID 24688858, 2014). "Transcriptome analysis of chlamydial growth in vitro has shown that there is highly upregulated gene expression of trmD (encoding a transfer RNA (tRNA) methyltransferase) associated with growth in the presence of IFNγ, thought to be important in the maintenance of chlamydial infection." (PMID 29482619, 2018). "Resistance to chlamydial infection is associated with increases in Th1 cytokines, such as IFNγ, which promote cytotoxic T cell responses; conversely, a Th2-dominated response, characterised by increased IL4 and promoted by IL10, is associated with persistence of infection." (PMID 27706211, 2016). "The decreased expression of IFNγ could make KoRV infected koalas more susceptible to persistent chlamydial infection, and a decrease in IL17A could make them more susceptible to gram negative bacterial, fungal and mycobacterial infection; but more tolerant of chlamydial infection." (PMID 31371797, 2019). "In this review, we discuss the natural history of genital chlamydial infections, morphological and molecular changes imposed by IFNγ on Chlamydia, and finally, the microenvironmental conditions associated with vaginal co-infections that can ameliorate the effects of IFNγ on C. trachomatis." (PMID 24918090, 2014). "Numerous cell types are capable of producing interferon gamma (IFN-γ) as a defense mechanism against chlamydial infection, thereby effectively mediating the clearance of infection." (PMID 41156830, 2025). "Specifically, ccr2 deficiency disrupts the differentiation and response of Th1 cells, which are the primary effector lineage responsible for clearing chlamydia through secretion of interferon-gamma (IFN-γ)." (PMID 39903705, 2025). "Since we were able to show Chlamydia-driven decreases in expression of JAK-STAT signaling factors and ISGs during chlamydial infection, we posited it would provide an advantage for Chlamydia under physiological levels of IFNγ." (PMID 39194253, 2024). "A key mechanism of IFNγ expression in chlamydial infections and disease is the conversion of tryptophan to kynurenine utilising IDO1/2 through the NAD biosynthesis pathway (Team, R.C, 2018)." (PMID 39600869, 2024). "We also assessed the systemic response by splenic T cells expressing cytokines with known importance to resolution of chlamydial infections and pathology; IFNγ, TNFα, IL17, IL13, IL10." (PMID 36799886, 2023). "Traditionally, the desired immune response to chlamydial infections has been identified as a T helper cell type 1 (Th1) cell-mediated response, with interferon gamma (IFN-γ) being the critical cytokine involved in chlamydial clearance." (PMID 33546104, 2021). "Several important cytokines or antibodies in response to chlamydial infection in koalas have been identified: IFNγ, IL17, IL10, tumor necrosis factor alpha (TNFα), IgG, and IgA." (PMID 33102563, 2020). "MPEG1 is inducible with IFNγ and type I interferons, both of which play important roles in limiting chlamydial infection in vivo." (PMID 32760406, 2020). "The immune response to Chlamydia has been studied extensively in humans and animal models and it is established that elimination of chlamydial infection is reliant upon Th1 cytokines, such as IFNγ, which promote cytotoxic T cell responses." (PMID 31371797, 2019).
chlamydial infection (continued). "The IFNγ-induced enzyme, indoleamine-2,3-dioxygenase-1 (IDO1), catabolizes tryptophan into kynurenine, and is proposed to be the primary mediator of the IFNγ-induced protective response against chlamydial infection." (PMID 29855501, 2018). "More recently, our and others' studies indicate that Th17 plays an important role in host defense against chlamydial infection through either promoting Th1-type cell responses or working synergistically with IFNγ." (PMID 29670466, 2018). "In genital chlamydia models, it has been shown that the enhancement of TNFα is also required for achieving protection against chlamydia and mechanisms that are nearly IFNγ independent but dependent on Plac8 and likely on T cell degranulation exist as well." (PMID 28678871, 2017). "IFNγ, one of the key cytokines of Th1 responses, is important in the control of chlamydial infections via several well-described mechanisms." (PMID 28678871, 2017). "The expression of the koala interferon gamma gene has been investigated because of its key role in the immune response to chlamydial infection." (PMID 25214207, 2014). "Although Ct infected cell lines are lysed in vitro, NK cells purified from the peripheral blood of individuals with current chlamydial infection had diminished lytic activity (and reduced IFNγ) compared with uninfected controls." (PMID 24651768, 2014). "In the studies in other hosts, an increase in IL10 production corresponded with a decrease in interferon-gamma (IFNγ) production, which is the principle Th1 cytokine that provides protection against chlamydial infection." (PMID 23527290, 2013). "Together, these studies suggest that IL-17, together with IFNγ, is important for macrophage activation, most likely M1 macrophages, to clear pulmonary chlamydial infection." (PMID 24073293, 2013). "In an attempt to mimic chronic chlamydial infections, Macaca nemestrina fallopian tubes received repeated C. trachomatis infections, which resulted in fibrosis and elevated IL-6, IL-10, IL-2, and IFNγ levels." (PMID 22894815, 2012). "Further, vaults induced markedly higher levels of IFNγ, necessary for eradication of chlamydiae, soon after infection in target tissue." (PMID 19404403, 2009). "However, the major player in clearing chlamydial infections remains the interferon-gamma (IFN-γ) produced by natural killer and T cells, via the depletion of critical nutrients for C." (PMID 41596756, 2026). "If KoRV infected koalas have a reduced IFNγ response when exposed to chlamydial infection this could result in increased dissemination, higher pathogen burden, prolongation of disease and increase in pathological lesions in these animals." (PMID 31371797, 2019). "Therefore, induction of the host tryptophan catabolizing enzyme, indoleamine-2,3-dioxgenase-1 (IDO1), by interferon gamma (IFNγ) is one of the primary protective responses against chlamydial infection." (PMID 29855501, 2018). "However, the sources of IFNγ and IL-17 production by which of γδ T cell subset in lungs and their biological activities following chlamydial infection remained unclear." (PMID 29670466, 2018). "Furthermore, IFNγ is increased in the conjunctivae of affected individuals during active chlamydial infection." (PMID 28678871, 2017). "Furthermore, studies on animal models have shown that local CD4+ cell response via the secretion of IFNγ and stimulation of other protective immune cells is required for a successful resolution of chlamydial infection." (PMID 28678871, 2017). "In this context interferon gamma (IFNγ) is the major host protective cytokine against chlamydial infections because it induces the expression of the host enzyme, indoleamine 2,3-dioxygenase 1, that degrades tryptophan, thereby restricting bacterial replication." (PMID 27658027, 2016). "In this review, we have described the mechanism by which IFNγ could act as a protective cytokine against chlamydial infections." (PMID 24918090, 2014).
chlamydial infection (continued). "Therefore, it is likely that natural immunity against chlamydial infections driven by a protective IFNγ response will be attenuated in patients that have BV, dependent on the bacterial representation within individual patients." (PMID 24918090, 2014). "Notably, nearly 40% of Th17 TRM co-expressed IL-17 and IFNγ by 14 days post-infection, suggesting that Th17 cells may contribute to IFNγ-mediated protection against chlamydial infection." (PMID 39203989, 2024). "CD8 T cells have conflicting roles in chlamydial infections, having been shown to cause immunopathology, predominantly through the production of TNFα, but in some cases also protection through atypical Chlamydia-specific cells secreting IL13 in addition to TNFα, IFNγ, and IL10." (PMID 36799886, 2023). "Interferon gamma (IFN-γ) is especially important in controlling the virulence of Chlamydia species and thus impacts the modeling of human chlamydial infection and disease in mice." (PMID 30967464, 2019). "Therefore, even if C. trachomatis possesses a mechanism to block the effect of IFNγ on an ongoing primary infection, the effects of the cytokine on bystander cells would block infection spread, consistent with overwhelming evidence that IFNγ is critical to control chlamydial infections in vivo." (PMID 29855501, 2018). "To explain the observations in the context of chlamydial infection and trachoma we propose a two-stage model of response and disease that balances the cytolytic response of KIR expressing NK cells with the ability to secrete interferon gamma, a combination that may cause pathology." (PMID 24651768, 2014). "Because IFNγ blocks spread of a primary infection, a corollary to our model predicts that chlamydial infection will not disrupt the nuclear localization of pSTAT1 activated by IFNγ prior to infection." (PMID 29855501, 2018). "Although antigen-specific IFNγ has been shown to be critical for protection against chlamydial infections, we did not observe any differences in IFNγ levels in tears between C. caviae infected and control animals." (PMID 28678871, 2017). "Both CD4+ cells and macrophages release interferon gamma (IFN-γ), which can resolve chlamydial infection or stimulate a non-replicative persistent state that can result in chronic infection that is likely resistant to antimicrobial treatment." (PMID 20543948, 2010). "In particular, in infections of intracellular bacteria which often bias a Th1-like response, such as chlamydia, B cells may more likely modulate immune responses through IFNγ, rather than IL-10 production." (PMID 37759658, 2023). "Additionally, IFNγ measurements have been shown to be dependent on the stage of chlamydial infection in mice and non-human primates, something that is currently uncontrollable in trials using free-ranging koalas." (PMID 33102563, 2020). "However, mice are able to resolve chlamydial infection in the absence of IFNγ, suggesting that while beneficial in the process of clearing chlamydial infection, it is not essential, and that there are T-and B-lymphocyte dependent mechanisms also playing roles." (PMID 25386180, 2014). "qPCR was used to examine mRNA expression for Th1 (IFNγ), Th2-promoting (IL6, IL10) and Th17 (IL17A) cytokines, along with CD4 and CD8 in whole blood of koalas (n = 74) from Mt Eccles and Raymond Island in Victoria, Australia, with and without natural chlamydial infection." (PMID 31371797, 2019).